ENSG00000280636
Synonyms: LOC124900526
Gene: Small nucleolar RNA gene on chromosome 2 (179,934,401 to 179,934,538, reverse strand). Ensembl gene ENSG00000280636.
Gene Ontology:
Biological process: RNA processing
Cellular component: nucleolus
Homologues: Paralogues in human: SNORA17B (80% identical), SNORA17A (56% identical).